POU2F3 (POU class 2 homeobox 3)
Diseases named in the same sentence as POU2F3 in open-access papers (continued):
Sharing a sentence is not in itself a finding about the gene and the disease.
melanoma (2 papers, 2016 to 2021). A malignant, usually aggressive tumor composed of atypical, neoplastic melanocytes. "Genes (e.g. BRN2, POU2F3, and SOX10) expressed in melanoblasts, and those (e.g. JARID1B, CD271, and ABCB5) which help to endow melanoma cells with stem-like properties and cellular plasticity, are also in this network." (PMID 27149382, 2016).
squamous cell carcinoma (2 papers, 2021 to 2023). A carcinoma arising from squamous epithelial cells. "POU2F3, which is required for the development and function of thymic tuft cells, was found to be highly expressed in thymic squamous cell carcinomas." (PMID 34778027, 2021). "Tuft cells have been identified in the thymic medulla, and evidence of POU2F3 expression in thymic squamous cell carcinomas supports the notion that these malignancies may acquire a tuft cell phenotype." (PMID 37190202, 2023).
thymic squamous cell carcinoma (2 papers, 2024 to 2025). "Previously, the expression of POU2F3 was observed only in 15∼20% of SCLC cases, 70% of thymic squamous cell carcinoma cases and castration-resistant prostate adenocarcinoma (CRPC) cases." (PMID 38649942, 2024).
viral infection (2 papers, 2018 to 2022). "We subjected Trp63CreERT2;Pou2f3-/-;R26Ai14 mutants and controls (Trp63CreERT2;Pou2f3+/-;R26Ai14) to viral infection followed by continuous Tmx injection from 14 to 18 dpi." (PMID 36129169, 2022). "(B) Lineage tracing of Pou2f3+ cells in the parenchyma after PR8 virus infection." (PMID 36129169, 2022).
adenoid cystic carcinoma (1 paper, 2024). A malignant tumor arising from the epithelial cells. "Only adenoid cystic carcinoma consistently expressed POU2F3 (5/5), however tumor cells were overall sparse and rarely formed homogeneously POU2F3-positive cell nests." (PMID 38358561, 2024).
adenoma (1 paper, 2012). A neoplasm arising from the epithelium. "The expression of the POU domain class 2 transcription factor 3 (POU2F3) was decreased in the adenoma and the tumorous colonic epithelia." (PMID 23049694, 2012).
asthma (1 paper, 2024). "We sought to determine the requirement of tuft cells for the RV-induced asthma phenotype in wild-type mice and mice deficient in Pou2f3, a transcription factor required for tuft cell development." (PMID 38061015, 2024). "We also determined the requirement of tuft cells for the RV-induced asthma phenotype in wild-type mice and mice deficient in Pou2f3, a transcription factor required for tuft cell development." (PMID 38061015, 2024).
autoimmune disease (1 paper, 2020). A disorder resulting from loss of function or tissue destruction of an organ or multiple organs, arising from humoral or cellular immune responses of the individual to their own tissue constituents. "Its receptor is known to play a pathogenic role in many inflammatory and autoimmune diseases and seems to be expressed by the PanIN cells with basolateral localization in the PKI;POU2F3+/+ tumors." (PMID 33086657, 2020).
benign salivary gland tumors (1 paper, 2024). "Next, we examined FOXI1 and POU2F3 expression in common benign salivary gland tumors: WTs, PAs, basal cell adenomas, and oncocytomas." (PMID 38358561, 2024).
co-infection (1 paper, 2024). "Unexpectedly, lower H. bakeri worm burdens were observed in the Pou2f3-/- mice compared to WT mice and worm counts in Pou2f3-/- mice were not affected by co-infection with H. diminuta." (PMID 39083533, 2024).
coronary thrombosis (1 paper, 2014). Coagulation of blood in any of the coronary vessels. "These SNPs are very close to the POU2F3 gene which is known to associate with coronary thrombosis." (PMID 25368629, 2014).
ductal breast carcinomas (1 paper, 2023). "This study demonstrated that POU2F3 expression occurs in the non-invasive stage of ductal breast carcinomas and rarely in HER2 + /HR + invasive breast carcinomas (so-called triple-positive), while it is prevalent in TNBCs." (PMID 37179317, 2023).
endometrial cancer (1 paper, 2023). Primary or metastatic malignant neoplasm involving the endometrium (mucous membrane that lines the endometrial cavity). "Among candidate genes, ARX, POU2F3, TLX2 and LIM1 were derived as molecules contributing to the malignant transformation of endometrial cancer." (PMID 36969081, 2023).
eosinophilia (1 paper, 2024). "Pou2f3+/+, but not Pou2f3-/-, mice infected with H. diminuta showed significant blood eosinophilia, which was not affected by praziquantel treatment." (PMID 39083533, 2024).
invasive breast carcinoma (1 paper, 2023). A carcinoma that infiltrates the breast parenchyma. "In the new cohort of invasive breast cancers, IHC revealed four POU2F3-positive cases, two of which were triple-negative, one luminal-type, and one triple-positive." (PMID 37179317, 2023).
oncocytoma (1 paper, 2024). "In addition, two basal cell adenomas (2/5) and one oncocytoma (1/3) also contained POU2F3-positive cells." (PMID 38358561, 2024).
pancreatitis (1 paper, 2020). Inflammation of the pancreas. "While 97% of pancreatitis tuft cells are Pou2f3 positive (189/195 cells, n = 4 mice), only 81% of Pou2f3 positive cells (118/145 cells, n = 4 mice) were determined to be tuft cells by co-expression of marker Cox1 (conducted in the CD-1 strain)." (PMID 32116793, 2020).
periodontitis (1 paper, 2019). An acute or chronic inflammatory process that affects the tissues that surround and support the teeth. "Mice lacking SCC taste signaling molecules (i.e., Gnat3−/− mice) or lacking SCCs (i.e., Pou2f3−/− mice) developed more severe ligature-induced periodontitis with an increased level of ABL compared with WT mice." (PMID 31582750, 2019).
salivary gland neoplasm (1 paper, 2024). Tumors of the SALIVARY GLANDS. "Instead, we believe that WTs characteristically have the strongest capacity to produce FOXI1- and POU2F3-positive cells among common salivary gland tumors." (PMID 38358561, 2024). "Finally, we statistically compared the expression status of FOXI1 and POU2F3 among different salivary gland tumors." (PMID 38358561, 2024). "In this study, we tested this hypothesis for salivary gland tumors using immunohistochemistry (IHC) for FOXI1 and POU2F3 because, as mentioned, both ionocytes and tuft cells are found in salivary glands." (PMID 38358561, 2024).
triple-negative breast carcinoma (1 paper, 2023). An invasive breast carcinoma which is negative for expression of estrogen receptor (ER), progesterone receptor (PR), and human epidermal growth factor receptor 2 (HER2). "Rare and mainly triple-negative breast cancers (TNBCs) were recently found to exhibit tuft cell-like expression profiles, including POU2F3, the tuft cell master regulator." (PMID 37179317, 2023).
tumor (46 papers, 2013 to 2025). "For example, some studies have reported that POU2F3-positive tumours are associated with improved survival, whereas others found improved outcomes or no significant prognostic difference." (PMID 40931642, 2025). "MAPK inhibition in NKX2-1-negative tumor cells was also associated with induction of several markers of chemosensory tuft cells, including the lineage specifier Pou2f3 as well as Gfi1b and Gnat3." (PMID 33821796, 2021). "GATM, ARHGEF26 and POU2F3 were associated with better survival, and were recognized as tumor suppressors." (PMID 34301206, 2021). "Therefore, including POU2F3 as a potential additional diagnostic marker might represent an appealing approach for the diagnosis of SCLC tumours that lack or exhibit minimal level of standard NE markers." (PMID 36149789, 2022). "As such, pharmacological inhibition of SWI/SNF ATPases (e.g., SMARCA4/2 inhibitors and BRD9 degraders) disrupts chromatin accessibility at POU2F3 regulatory loci, leading to transcriptional reprogramming and impaired tumor growth." (PMID 40333678, 2025). "Targeting the POU2AF2–SWI/SNF axis presents a promising therapeutic strategy for inhibiting POU2F3-driven tumor progression in SCLC-P." (PMID 40333678, 2025). "AU24118 also downregulates POU2F3 and its coactivator, resulting in the reduction of tumor volume and weight." (PMID 41278204, 2025). "This PARCB model generates two distinct tumor lineages characterized by either stem-like (POU2F3/ASCL2 subtype) or neuroendocrine features (ASCL1 subtype) that closely resemble the POU2F3 and ASCL1 subtypes seen in clinical SCNCs." (PMID 39589879, 2024). "The observed mutually exclusive expression of two master regulators, FOXI1 and POU2F3, in different cell types in WTs seems unusual for a true (i.e., clonal) neoplasm and is consistent with the idea that WT is a reactive lesion." (PMID 38358561, 2024). "POU2F3 expression was consistent during tumor relapse, with a consistent expression level in some of the malignant cells from both the PT and RT." (PMID 36195615, 2022). "Like in BPN tumors, these POU2F3-positive cells were relatively rare (~5% or less of tumor cells overall)." (PMID 33821796, 2021). "(C) Violin plots of single-cell sequencing data showing expression levels of Gkn1, Tff1, Tff2, Cym, Pgc, Pga5, and Pou2f3 transcripts in BPN tumor clusters 1–3 and highlighting key drug-mediated cell-identity changes." (PMID 33821796, 2021). "According to a recent study, MYC can act as a master regulator for NE-differentiation and can dynamically shift tumor phenotype acting on the NOTCH signaling pathway from ASCL1 + NEUROD1+ (NE-high) to YAP1+ or POU2F3+ (NE-low)." (PMID 34200100, 2021). "In contrast, a small subset of control BPN tumor cells were POU2F3 positive, and the fraction of positive cells was higher upon MAPK inhibition (lower row)." (PMID 33821796, 2021). "Indeed, ASCL1 overexpression in two PARCB POU2F3/ASCL2 tumor-derived cell lines led to increased PGC-1α expression in both cell lines." (PMID 39589879, 2024). "POU2F3 was predominantly expressed in the cytoplasm of tumor cells." (PMID 35220975, 2022). "Tumor-infiltrating CD4+ T cells (C12_CD4) were associated with binding motif enrichment for cluster-specific TFs such as members of the POU domain family (POU2F1, POU2F2 and POU2F3), in addition to TF programs shared with dysfunctional CD8+ T cells." (PMID 35668194, 2022). "Notably, this was not only seen in ASCL1+ tumors (for example, SCLC-04, NE score 0.4) but also in the POU2F3+ tumor with a positive NE-score (SCLC-15, NE score 0.26)." (PMID 33750914, 2021). "Interestingly, we detected a minor population of POU2F3-positive tumor cells in seven NKX2-1-positive cases." (PMID 33821796, 2021). "Although, tumor growth is not significantly modified, development of liver metastasis was almost inhibited in POU2F3 deficient mice." (PMID 33086657, 2020).
tumor (continued). "This approach allowed us to show that the inflammatory and immune response observed in PDAC from POU2F3 deficient mice has been triggered directly from the tumor site and not through some alterations of the hematopoiesis." (PMID 33086657, 2020). "Therefore, based on the morphology and location of tumor cells, the strong positive expression of POU2F3 in tumor cells may be a specific marker for SCLC." (PMID 38649942, 2024). "CU-PC01 tumours display DNPC-like clinicopathological features, including the absence of AR, PSA and PSMA, loss of PTEN and RB, and a lack of NE markers, including SYP, neuronal differentiation 1 (NEUROD1), POU class 2 homeobox 3 (POU2F3) and achaete-scute homolog 1 (ASCL1)." (PMID 38667288, 2024). "Each of these subtypes is defined by its inter tumor expression levels of the four key transcription regulators: Achaete–Scute Family BHLH Transcription Factor 1 (ASCL1), Neuronal Differentiation 1 (NEUROD1), POU Class 2 Homeobox 3 (POU2F3), and yes–associated protein 1 (YAP1)." (PMID 33809582, 2021). "We conclude that although POU2F3 deficiency does not influences tumor growth, it could play an essential role in metastasis development." (PMID 33086657, 2020). "Clinically, tumor tissue immunohistochemistry (IHC) staining is used to measure the protein expression of four transcription factors (ASCL1, NEUROD1, POU2F3, and YAP1) to identify SCLC subtypes." (PMID 40285610, 2025). "Next, PGC-1α was overexpressed specifically in POU2F3/ASCL2 and ASCL1 PARCB tumor-derived cell lines, and its effects on OXPHOS activity and neuroendocrine differentiation were measured." (PMID 39589879, 2024). "Because the proportion of immunoreactive cells and the H-scores for FOXI1 and POU2F3 were generally low, even in WTs, we cannot state that the tumor cells in WTs diffusely express FOXI1 and POU2F3." (PMID 38358561, 2024). "Cluster 4 was predicted to be a goblet cell-like cluster because it was enriched with tumor suppressors and developmental transcription factors for intestinal cells, such as SPDEF or POU2F3, and goblet cell markers." (PMID 38084922, 2023). "In particular, we confirmed that KIT‐targeting drugs, such as pazopanib, are potentially adequate to target POU2F3‐driven SCLCs, whereas YAP1‐driven tumours are more resistant to vorinostat (targeting HDAC1)." (PMID 36149789, 2022). "Notably, SCLC tumour cells expressing ASCL1 and NEUROD1 exhibit neuroendocrine features whereas those expressing YAP1 and POU2F3 exhibit a neuroendocrine low phenotype." (PMID 39567755, 2025). "Instead, a group of SCLC tumours was identified with low expression of ASCL1, NEUROD1 and POU2F3." (PMID 39567755, 2025). "This discrepancy underscores that the prognostic and immunological characteristics of POU2F3-positive tumours are not universal but are determined by the unique biological context and aetiology of the primary organ." (PMID 40931642, 2025). "One case (1.96%) had an expression of both ASCL1 and POU2F3, but this expression was present in different regions of the tumor and did not overlap." (PMID 39682568, 2024). "Immunohistochemically, the tumor cells were positive for cytokeratin, TTF-1, POU2F3, LCA, and CD43." (PMID 38649942, 2024). "CDX13, the only non-NE POU2F3 subtype CDX8 was the only model with REST expressed throughout the tumor, in which VM vessels were abundant (VM vessel score 38%) and co-localized with REST." (PMID 37455012, 2023). "In addition, key TFs related to SCLC tumor subtypes, such as ASCL1, NEUROD1, and POU2F3, were found to be differentially expressed in our cohort, as further described in the following sections." (PMID 36195615, 2022).
tumor (continued). "Both Pepsinogen C and POU2F3-positive cells were found in alveolar hyperplasia induced by Nkx2-1 deletion, consistent with the microscopic similarity between these hyperplasia and residual MAPKi-treated BPN tumor cells." (PMID 33821796, 2021). "We would assume that knocking out POU2F3 might have an effect on the global immune system development from the hematopoiesis that could explain the differences seen in the tumor adaptive response between PDAC of PKI;POU2F3+/+ and PKI;POU2F3−/− mice." (PMID 33086657, 2020). "In the current study, using TMAs and specimen slides from a relatively large cohort (N = 192) of primary resected SCLC, we assessed the tumor‐derived protein expressions of ASCL1, NEUROD1, POU2F3, YAP1 as well as VIM, a mesenchymal marker which may be a potential assay to define SCLC‐I." (PMID 37789961, 2023). "Our data revealed that ASCL1, NEUROD1, and POU2F3 were exclusively expressed in the malignant cells of SCLC tumors, however, YAP1 was mainly expressed in normal epithelial cells rather than tumor cells." (PMID 36195615, 2022). "The SCLC-P tumor, with no detectable expression of ASCL1 and NEUROD1, consisted of individual cells expressing heterogeneous levels of POU2F3, with half of the cells having no detectable expression of POU2F3." (PMID 36195615, 2022). "While ATOH1 CDXs expressed neither ASCL1 nor POU2F3, ATOH1 was expressed alone (CDX17P) or in combination with NEUROD1 at the transcript and protein levels (CDX25, 78% positive tumor cells; CDX30P, 78% positive tumor cells; CDX17, moderate NEUROD1 expression, 30% positive tumor cells)." (PMID 40305287, 2025).